BCR (BCR activator of RhoGEF and GTPase)
Diseases named in the same sentence as BCR in open-access papers (continued):
Sharing a sentence is not in itself a finding about the gene and the disease.
acute myeloid leukemia (69 papers, 2007 to 2026). Acute myeloid leukemia (AML) is a group of neoplasms arising from precursor cells committed to the myeloid cell-line differentiation. "Acute myeloid leukemia (AML) with BCR::ABL1 fusion is a rare but high-risk entity characterized by aggressive disease progression and poor response to conventional therapies." (PMID 41245943, 2025). "Furthermore, given that Evi1 heterozygosity ameliorates CML-CP and CML-BC development and that the combination of Evi1 and BCR–ABL causes acute myeloid leukemia resembling CML-BC, Evi1 could regulate CML development as a potent driver." (PMID 24747972, 2014). "Acute myeloid leukemia (AML) with BCR::ABL1 fusion occurs only in < 1% of de novo patients with AML." (PMID 38633128, 2024). "BCR::ABL1 fusion is found in < 1% of de novo acute myeloid leukemia (AML) cases and confers a poor prognosis." (PMID 38633128, 2024). "Acute myeloid leukaemia with BCR::ABL1 fusion is a defined genetic entity in the fifth World Health Organization classification." (PMID 38550948, 2023). "Acute myeloid leukemia (AML) with BCR::ABL1 has recently been recognized as a distinct subtype in international classifications." (PMID 37895120, 2023). "Examples of such “precision medicine” include the BCR-ABL fusion gene in chronic myeloid leukemia (CML), PML-RARA fusions in acute promyelocytic leukemia (APL) and FLT3 mutations in acute myeloid leukemia (AML)." (PMID 34425749, 2021). "Here, we report a 35-year-old Chinese female patient who was diagnosed as acute myeloid leukemia with BCR/ABL expression." (PMID 32871908, 2020). "Instead, other reports show that ALOX5 may have opposite roles in a different context that it promoted BCR-ABL driven B-cell acute lymphoblastic leukemia while inhibited MLL-fusion driven acute myeloid leukemia." (PMID 36750552, 2023). "The diagnosis of acute myeloid leukemia with BCR/ABL expression was established." (PMID 32871908, 2020). "We recently reported a de novo acute myeloid leukemia (AML) patient harboring both BCR::ABL1 p190 isoform and RUNX1::MECOM fusion, a rare and high-risk molecular profile." (PMID 41245943, 2025). "Univariable analyses of overall survival, relapse, and non‐relapse mortality rates after 3 years in acute myeloid leukemia (AML) with BCR::ABL1 group." (PMID 38633128, 2024). "We present a case report of a patient with acute myeloid leukemia (AML) characterized by the simultaneous presence of nucleophosmin 1 (NPM1) mutation and the breakpoint cluster region-Abelson (BCR-ABL) fusion oncogene." (PMID 31110828, 2019). "For comparison, we present here a patient with BCR::ABL1‐positive acute myeloid leukemia (AML)." (PMID 39932124, 2025). "Using GAB2 deficient mice, we previously showed that GAB2 serves as an important effector of the oncogenic FLT3-ITD receptor tyrosine kinase in acute myeloid leukemia (AML) and of BCR::ABL1 in CML." (PMID 37161070, 2023). "Dasatinib, an FDA-approved multi-targeted kinase inhibitor of BCR/ABL and Src kinases was reported to induce ERK phosphorylation in acute myeloid leukemia (AML) and during stimulated pigmentation of ex vivo cultured skin." (PMID 35164068, 2022). "The fusion proteins in AML like Breakpoint Cluster Region-Abelson Murine Leukemia (BCR-ABL) and Acute Myeloid Leukemia-Eight Twenty-One (AML-ETO) have a significant role in the upregulation of the gene associated with AML cases." (PMID 35788450, 2022). "When screening our databases for patients for this study, we also identified patients who had history of CML and later developed de novo myelodysplastic syndrome (MDS) or acute myeloid leukemia (AML), with low BCR::ABL1 levels (<1% IS)." (PMID 36307398, 2022).
acute myeloid leukemia (continued). "Aberrant chromosomal translocation BCR–ABL kinase and activation of FMS-like tyrosine kinase 3 (FLT3) receptor tyrosine can induce STAT 5 activation in CML and Acute myeloid leukemia (AML), respectively." (PMID 30847297, 2019). "High levels of SOCS2 was identified as an adverse prognostic characteristic of acute myeloid leukemia (AML) and ALL, such as those with MLL rearrangement or BCR/ABL fusions." (PMID 31523525, 2019). "TKIs are used in first-line for chronic and acute myeloid leukemia (CML and AML) with BCR/ABL overexpression as well as for gastrointestinal stromal tumors (GIST) with c-KIT mutations." (PMID 23316191, 2012). "An example of the successful use of a mouse model in translational cancer research is the modeling of the BCR-ABL translocation and the efficiency of the kinase inhibitor Gleevec to treat acute myelogenous leukemia (AML)." (PMID 22111002, 2011). "TF1 (human erythroleukemia), HEL (human erythroid leukemia), and F36P (MDS-RAEB) showed varying levels of PTBP2 expression, whereas HNT34 (BCR::ABL1+ human Acute Myeloid Leukemia) cells showed almost no PTBP2 expression among the four AML cell lines." (PMID 40113750, 2025). "The distribution of RUNX1-RUNXT1, PML-RARA, CBFB-MYH11, BCR-ABL1p210, and KMT2A-MLLT3 in the pediatric population with acute myeloid leukemia (AML) in many countries of Latin America is largely unknown." (PMID 36452349, 2022). "In acute myeloid leukemia (AML), ROCK1 depletion by genetic knockout or ROCK inhibition with H-1152, Y27632, or fasudil reduced the survival of malignant cells bearing oncogenic form of KIT, FLT3, and BCR-ABL through suppressing MLC phosphorylation." (PMID 26725045, 2016). "We also measured SPARC level in BCR/ABL positive cell lines (K652, LAMA84) and in HL60, a BCR/ABL negative acute myeloid leukemia cell line." (PMID 23383963, 2013). "According to multiplex PCR, all 135 screened samples were negative for the most frequent PGF of B-lineage ALL: TEL-AML1, E2A-PBX, MLL-AF4, and BCR-ABL (p190) and for the most frequent PGF of acute myeloid leukemia (AML): AML-ETO, PML-RARA, and CBFβ-MYH11." (PMID 24621554, 2014). "Overall findings were consistent with Acute Myeloid Leukemia with monocytic differentiation with features favoring evolvement on top of CML (blast phase), but another differential diagnosis of de novo AML with BCR/ABL1 could not be excluded entirely during diagnostic workup." (PMID 37234472, 2023). "Chronic myeloid leukemia (CML) is driven by the BCR::ABL fusion tyrosine kinase and progresses gradually from a chronic phase of excessive mature myeloid cell proliferation to a fatal blast crisis (BC) resembling acute myeloid leukemia (AML), which is characterized by impaired differentiation." (PMID 41179655, 2025).
lymphoma (56 papers, 2009 to 2026). A malignant (clonal) proliferation of B- lymphocytes or T- lymphocytes which involves the lymph nodes, bone marrow and/or extranodal sites. "The diagnosis of B-LBL has mostly depended on the characteristics of B-lymphoblast leukemia/lymphoma by IHC and a complete range of immunopheotyping, in addition to the molecular finding of the BCR/ABL gene mutation." (PMID 34115047, 2021). "The requirement for multiple BCR alterations in combination with proper LC usage might contribute to the only moderately elevated lymphoma risk of patients with HCV." (PMID 39082968, 2024). "Some other lymphoma cases involve deregulated signaling by mutated components of the BCR cascade." (PMID 25229630, 2014). "Consequently, inactivating mutations or downregulation of these immune checkpoints might provide a mechanism for stimulating BCR-associated mitogenic signals in lymphoma cells." (PMID 37041226, 2023). "CARD11, which is associated with lack of response to ibrutinib, encodes a scaffold protein required for BCR activation of NF‐κB signaling and implicated in lymphoma tumorigenesis, indicating that resistance to ibrutinib may be more closely linked to NF‐kB‐related pathways in the tumor." (PMID 34791836, 2022). "The expression of myeloid antigens CD13 and CD33 in B-lymphoblastic leukemia/lymphoma is typically observed in B-lymphoblastic leukemia/lymphoma with BCR::ABL1 fusion." (PMID 40227608, 2025). "It has been reported to interact directly with Bruton's tyrosine kinase (BTK) and participate in the BCR signaling pathway—one of the critical survival pathways in lymphoma." (PMID 40993727, 2025). "B-lymphoblastic leukemia/lymphoma with BCR::ABL1-like features exhibits a CRLF2 gene rearrangement in 50% of cases, leading to an overexpression of CRLF2 protein, which can be assessed by flow cytometric analysis." (PMID 40227608, 2025). "The frequency of lymphoma reprogramming is expected to grow in the era of targeted therapies, particularly in monotherapy targeting a member of BCR-dependent cell signaling pathways." (PMID 38638855, 2024). "Differentially regulated genes were enriched for classical lymphoma driver genes downstream of the BCR, including MALT1 and CARD11, as well as NFATC2, TNFRSF13C (BAFF), and components of the NF-κB (RELB, IRAK1, BCL3, and TNFRSF1B) pathway." (PMID 39082968, 2024). "Studies have shown that the BCR signaling pathway plays an important role in the pathogenesis and progression of MCL, with activated BCR signaling found in B cells in lymphoma." (PMID 38268531, 2024). "The BCR of lymphoma cells represents an ideal target for new therapeutic approaches and different BCR‐targeting therapeutic formats like anti‐idiotype antibodies and peptibodies have been developed with moderate clinical success." (PMID 36819155, 2023). "Antigenic BCR stimulation by autoantigens has been proposed as pivotal pathway for malignancy in several types of lymphoma." (PMID 36819155, 2023). "These highly selective cytotoxic effects show that BAR‐bodies target lymphoma cells via their BCR with highest specificity." (PMID 36819155, 2023). "As expected, BCR- lymphoma cells show decreased levels of GSK-3β phosphorylated on Ser9 through PI3Kδ/phosphoinositide-dependent kinase 1 (PDK1)/Akt signaling." (PMID 35681507, 2022). "In DLBCL, self-antigens that are either present on the BCR itself or in apoptotic debris of the tumor cells have been proposed to promote the activation of the lymphoma cells." (PMID 35203553, 2022). "ITPKB has been shown to be a negative regulator of the BCR/NF-κB signaling pathway which is very important for the growth and survival of lymphoma cells." (PMID 36306325, 2022). "The BCR- lymphoma cells display a rewiring of their metabolism, consisting in upregulated glutaminolysis and increased fueling of both glucose and exogenous pyruvate into the tricarboxylic acid (TCA) cycle." (PMID 35681507, 2022).
lymphoma (continued). "Either GSK-3β genetic knockdown or chemical inhibition by CHIR99021 rescues the proliferative capability of BCR- lymphoma cells to levels similar to those of BCR+ cells." (PMID 35681507, 2022). "Correspondingly Pla2g2a+ BALB/c and C.B17 mice showed increased B1a cells in neonatal adults and certain BCR B1 B cells generated CLL/lymphoma in old age as found in unmutated CLL in humans." (PMID 36050343, 2022). "In a mouse model of GC-derived lymphoma, there was an increase in the proliferation of B cells under BCR stimulation compared to that in wild-type mice." (PMID 34206047, 2021). "The CDR3 hypervariable regions of immune receptors (T-cell receptor, TCR or B-cell receptor, BCR) in the context of T- or B-cell leukaemia or lymphoma are targetable and specific sequences, similar to cancer mutations." (PMID 34371731, 2021). "The BCR signaling mainly influences the survival and growth of B‐cell leukemia or lymphoma cells, while the tumor‐infiltrating B cells were reported to promote tumor growth in SCC and pancreatic cancer." (PMID 33987946, 2021). "A key molecular feature of these lymphomas pertains to the identification of SHM imprints within the variable domain of the clonotypic BcR IG, alluding to antigen exposure." (PMID 32083012, 2020). "Extensive immunogenetic profiling of MZ lymphomas and cross-comparison to other B-NHLs has also documented the existence of rare public BcR IG stereotypes shared by different entities." (PMID 32083012, 2020). "Enforced expression of Arid3a also augmented the capacity of the TCL1 Tg to promote B CLL/lymphoma, including those expressing the VH12+ aPtC BCR as previously found among the B1a cell-derived B CLL/lymphoma in TCL1 Tg+ mice." (PMID 30930899, 2019). "Many lymphomas manifest “chronic‐active” BCR signaling that is reminiscent of antigen‐dependent BCR and PI3K signaling." (PMID 30874354, 2019). "This tonic BCR signaling is typical of B1 and follicular B cells (reviewed in135) but both active and tonic BCR signaling can be hijacked by GC‐derived lymphomas to promote survival." (PMID 30874354, 2019). "Together, our results indicate that GCN5/PCAF inhibition attenuates BCR signaling in lymphoma cells, including tonic signaling upon which BL cells depend." (PMID 31645904, 2019). "Because of a generalized lymphadenopathy noted at the time of diagnosis, a lymph node biopsy was also performed, which revealed a T-cell lymphoblastic leukemia/lymphoma, BCR/ABL1 positive, with clonal evolution." (PMID 30581639, 2018). "At the same time, TAK1 activity induces JNK signaling and both processes are required to induce cell death, and thereby counterselect BCR-addicted lymphoma cells." (PMID 30022982, 2018). "We identified a specific cluster of genes that was coherently expressed in primary lymphoma samples and suppressed by activation of the B cell receptor (BCR) through αIgM treatment of lymphoma cells in vitro." (PMID 27166259, 2016). "Except for very immature proliferations, most cases of B cell malignancies feature expression of Ig, either in the form of a membrane-anchored pre-BCR / BCR for lymphomas or as secreted Ig for plasma cell proliferations." (PMID 25229630, 2014). "Here we investigated the effects of STAT3 deletion in a BCR/ABL-induced lymphoma model, which is tightly controlled by natural killer (NK) cells in vivo." (PMID 24473086, 2014). "For example, formation of de novo C16- and/or C24-Cer induces apoptosis in lymphoma cells in response to BcR triggering, in prostate carcinoma cells by androgen deprivation and MDA-7/IL-24 stimulation, and in neutrophils by serum depletion." (PMID 23091403, 2012). "Studies in B-cell receptor (BcR-) activated lymphoma cells have shown that de novo Cer formation induces degradation of XIAP in a proteasome-dependent manner." (PMID 23091403, 2012).
lymphoma (continued). "B-lymphoblastic leukemia/lymphoma with BCR::ABL1 fusion has also been reported to exhibit a decreased expression of CD9 and CD81 when compared with cases of B-lymphoblastic leukemia/lymphoma without cytogenetic alterations or with other cytogenetic abnormalities." (PMID 40227608, 2025). "The IL4 and BCR-induced mTOR activation was reduced by CREBBP mutants and augmented by mutant STAT6, establishing a link between STAT6 mutations and mTOR regulated pro-growth pathways in lymphoma." (PMID 39910284, 2025). "Yet, it remains unclear whether the BCR expressed by the lymphoma cell directly (cross-)reacts with HCV antigens, what consequences may arise from such an interaction, or if the mechanisms underlying clonal B cell selection may be more indirect." (PMID 39082968, 2024). "Lymphomas employ the entire spectrum of signaling mechanisms for survival and growth, spanning from antigen dependence to antigen receptor-dependence in an antigen-independent manner, to reliance on signaling pathways activated independently of BCR or TCR." (PMID 38638855, 2024). "There is a high-frequency set of mutated genes in HBsAg-positive DLBCLs that may affect multiple key pathways involved in lymphoma development, such as epigenetic regulation, DNA damage repair, BCR/NF-kB, and immune evasion." (PMID 38318173, 2024). "We identified changes in NF-kB/MAPK and Jak-Stat/BCR pathways pertinent to lymphoma pathogenesis." (PMID 37568720, 2023). "Alternatively, BCR-based selection may be impaired, if it operates at all, in FL clones, as in other lymphomas." (PMID 36439408, 2022). "Molecular techniques emphasizing clonality of lymphocytes such as BCR sequencing, analysis of immunoglobulin gene rearrangements in CSF or in biopsy specimens, could better facilitate the diagnosis of lymphoma." (PMID 35418930, 2022). "Another role identified for FBXO10 in human lymphoma cell lines is in the negative regulation of BCR signalling via BCR signalling-induced membrane re-localisation followed by degradation of human germinal-centre associated lymphoma (HGAL, also called GCET2) protein levels." (PMID 33914737, 2021). "On the other hand, the finding that CLL stereotyped BcR IG also can be expressed by MZ lymphoma clones, albeit rarely, suggests that B cell clones carrying certain BcR IG may give origin to different lymphoproliferations." (PMID 32156260, 2020). "Next, we investigated whether BCR activation affects the same genes in lymphoma precursor cells in the same way as in cultured lymphoma cells." (PMID 27166259, 2016). "In some cases of human lymphomas involving Epstein-Barr virus transformation, BCR-dependent activation or survival signals may be replaced by surrogate signals provided by the viral protein LMP2A." (PMID 25229630, 2014). "M-bcr breakpoints occur downstream of exon 13 (e13) or exon 14 (e14) of the BCR gene, producing the p210 fusion protein, which is found in 97–99% of CML cases and in 40% of adult and 10% of pediatric B-lymphoblastic leukemia/lymphoma (B-ALL) patients." (PMID 40507313, 2025). "We show that IL4 treatment induced RRAGD expression, that RRAGD is required for mTOR activation in lymphoma cells and that IL4-enhanced BCR signaling induced mTOR activation." (PMID 39910284, 2025). "In other lymphomas, such as mantle cell lymphoma (MCL), chronic activation of BCR signaling and MALT1 activity have been detected, but the molecular cause currently remains elusive." (PMID 35203553, 2022). "We obtained cell lines derived from conditional Tet-O transgenic murine models of lymphoma driven either by MYC, RAS or BCR-ABL and examined early and late FA synthesis gene profiles." (PMID 34399819, 2021). "In parallel, signatures such as stroma, host response, OxPhos and BCR/proliferation or Jak/STAT and IKK have been described by comprehensive consensus clustering, and identify the lymphoma microenvironment as a defining feature." (PMID 27166259, 2016).